NOLC1 (nucleolar and coiled-body phosphoprotein 1)
Diseases named in the same sentence as NOLC1 in open-access papers (continued):
Sharing a sentence is not in itself a finding about the gene and the disease.
infection (1 paper, 2017). The state of being infected such as from the introduction of a foreign agent such as serum, vaccine, antigenic substance or organism. "Therefore, we envision that when NS1 is expressed during infection, it binds to a variety of host proteins and inhibits host protein synthesis, including NOLC1." (PMID 29212246, 2017). "The collective data indicate that although NS1 protein plays an active role in IAV infection, the interaction between NS1 and NOLC1 has a negative impact on infection." (PMID 29212246, 2017). "Based on these data, it was concluded that during the process of infection, NS1 protein interacts with NOLC1 protein, reducing the level of NOLC1, and that the interaction between the two proteins promotes apoptosis of host cells, thus reducing the proliferation of the virus." (PMID 29212246, 2017).
NOLC1 also shares sentences with these, for which no sentence is quoted: cervical cancer (2 papers); lung adenocarcinoma (2); melanoma (2); adenocarcinoma (1); bile duct cancer (1); colon cancer (1); endometrial cancer (1); endometriosis (1); leukemia (1); liver cancer (1); neuroblastoma (1); renal cell cancer (1); thyroid cancer (1).